HES6 (hes family bHLH transcription factor 6)
Diseases named in the same sentence as HES6 in open-access papers (continued):
Sharing a sentence is not in itself a finding about the gene and the disease.
cancer (16 papers, 2009 to 2025). A tumor composed of atypical neoplastic, often pleomorphic cells that invade other tissues. "As previously indicated, HES6 expression is increased and associated with a poor prognosis in some cancers." (PMID 35673577, 2022). "HES6 has also been shown to be regulated by hypoxia-inducible factor (HIF1a) 65, which mediates the hypoxic response, a central hallmark of cancer progression and dissemination." (PMID 35673577, 2022). "The WNT/β-catenin signaling pathway, which can promote cancer metastasis 70, has been described to mediate the protumorigenic effects of HES6." (PMID 35673577, 2022). "Cells in cluster 5 resembled those in cluster 7 of DNs, and included cells with aberrant neuronal identity that expressed neuronal genes (GAP43, NEFM, DCX, HES6) and cancer-related proliferative genes (CRABP1, MYC, SFRP1)." (PMID 33771987, 2021). "Cluster 7 included cells with aberrant neuronal identity that expressed neuronal development genes (NEFM, DCX, STMN2, HES6) but also cell cycle and cancer-related genes (CRABP2, CCND1, MYC)." (PMID 33771987, 2021). "The target gene was hairy and enhancer of split family basic helix-loop-helix transcription factor 6 (HES6), a member of the HES family, and has been implicated in many cancers." (PMID 33681178, 2020). "In this paper, we discovered that CCMAlnc displayed decoy activity for miR-5001-5p and, in doing so, regulated its target HES6 in a molecular circuitry affecting the cancer malignance program." (PMID 33681178, 2020). "Other Notch targets (HEY1, HEY2 and HES4) also exhibited increased transcript levels in cancer cells compared to benign prostate cells, though the differences in expression were less dramatic than that observed for HES6." (PMID 25864518, 2015). "In agreement with these in vitro results, immunohistochemical assays revealed significantly reduced HES6 protein levels in cancers from men who had undergone long-term androgen deprivation therapy (ADT) compared to ADT-naïve cancers." (PMID 25864518, 2015). "To better understand HES6’s role in cancer progression, we analysed global gene expression in cells engineered to overexpress or knock down HES6 and compared the data sets to identify genes differentially expressed in the two cell types." (PMID 25864518, 2015). "Whereas HES6 overexpression or knockdown did not have a noticeable effect on cell viability or growth rate, HES6 levels significantly affected the ability of cancer cells to invade." (PMID 25864518, 2015). "Moreover, the genes HES6, SHISA2, PMP22, and IL1RL1 are primarily associated with the progression of cancer and diseases." (PMID 39336820, 2024). "Nevertheless, it might play a broad role due to amplification of the genomic region where HES6 is located in several cancers." (PMID 35673577, 2022). "The clinical significance and biological role of HES6 in human cancers remain poorly elucidated." (PMID 35673577, 2022). "Moreover, functional studies have revealed an important role for HES6 in supporting the growth and motile ability of cancer cells." (PMID 35673577, 2022). "The target gene HES6 was reported to play a vital role in different kind of cancer." (PMID 33681178, 2020). "A comparison of gene expression in benign versus malignant prostate cell lines identified HES6 as the most differentially expressed gene: HES6 transcripts were virtually undetectable in benign cells but yielded 4-fold higher transcript levels in cancer cells." (PMID 25864518, 2015). "Furthermore, the authors showed that Hes-6 is upregulated in several types of human cancers compared with normal tissue." (PMID 19891787, 2009). "Nevertheless, this is the first study in which the function of Hes-6 in cancer is described." (PMID 19891787, 2009). "We investigated the expression of Hes-6 in normal breast tissue compared with cancer tissue." (PMID 19891787, 2009).
cancer (continued). "HES6 appears to be a valuable prognostic biomarker that could enable patient stratification for adjuvant treatment, and it may be a valuable therapeutic target in different cancers." (PMID 35673577, 2022). "And whether the lncSHRG/SATB1/HES6 axis works in other cancers remains to be elaborated." (PMID 29050307, 2017). "Of 100 cancers with 50 PSA failures assigned the SIG-DESNT signature (DESNT), 61(37 PSA failures) were also detected by at least one of the SIG-HES6 signatures (HES6, Prolaris, and/or NMF1)." (PMID 32708551, 2020). "Stratifications using SIG-HES6 (HES6, PCS1, Prolaris) and SIG-DESNT (DESNT) classifiers frequently detected the same individual high-risk cancers, indicating that the underlying mechanisms associated with SIG-HES6 and SIG-DESNT may act together to promote aggressive cancer development." (PMID 32708551, 2020). "In these cell lines, HES6 regulated a set of genes that only partially overlapped with those found in PC3 cells, but the most highly affected pathways in all cancer cell lines were strikingly similar." (PMID 25864518, 2015). "Another important gene downstream of HES6 is NESTIN, a marker for cancer stem cells." (PMID 35673577, 2022). "Returning to the comparisons of cancers detected by the SIG-DESNT and SIG-HES6 groups of signatures, we combined data from the CancerMap, CamCap and MSKCC datasets (n = 482 patients) with PSA failure as an end point, and then separately applied the DESNT, HES6, NMF1, and Prolaris tests." (PMID 32708551, 2020). "In contrast to canonical Notch targets, HES6, a HES family member known to antagonize Notch signalling, was not regulated by Notch signalling, but relied instead on androgen levels, both in cultured cells and in human cancer tissues." (PMID 25864518, 2015). "Hes-6 has been described as an inhibitor of Hes-1 during neuronal development, although its function in cancer is not known." (PMID 19891787, 2009). "Finally, one might envision applying a network pharmacology strategy to simultaneously target HES6 and/or other NOTCH-related targets, which may produce therapeutic synergistic effects and translate into better therapeutic efficacy in different cancers." (PMID 35673577, 2022).
HES6 also shares sentences with these, for which no sentence is quoted: colorectal cancer (2 papers); neuroblastoma (2); brain cancer (1); coronary artery disease (1); infantile hemangiomas (1); metastatic disease (1); oral squamous cell carcinoma (1); prostate adenocarcinoma (1); retinoblastoma (1); splenic marginal zone lymphoma (1); thyroid cancer (1).